GFAP (glial fibrillary acidic protein)
Diseases named in the same sentence as GFAP in open-access papers (continued):
Sharing a sentence is not in itself a finding about the gene and the disease.
subarachnoid hemorrhage (14 papers, 2007 to 2025). A serious neurological disorder characterized by intracranial hemorrhage into the subarachnoid space. "The three diagnostic groups displaying the highest GFAP mean values were bacterial meningitis (0.18±0.33 μg/l), subarachnoid hemorrhage (0.13±0.23 μg/l), and status epilepticus (0.12±0.11 μg/l)." (PMID 23626774, 2013). "Levels of serum GFAP are higher in patients who experience secondary ischemia after subarachnoid hemorrhage." (PMID 26714784, 2015). "The increase in blood GFAP levels after acute brain conditions, such as subarachnoid hemorrhage and traumatic and hypoxic brain injury, has been extensively documented, but this increase may come through other mechanisms, such as a trauma-induced temporary opening of the blood-brain barrier." (PMID 34661615, 2021). "Other blood-based biomarkers including the Glial Fibrillary Acidic Protein (GFAP), the Neuron-Specific Enolase (NSE), and the S100b protein have been also evaluated as prognostic factors for patients with traumatic brain injury and subarachnoid hemorrhage." (PMID 39514015, 2024). "GFAP and UCH-L1 demonstrated a significant correlation with the dispersion of blood volume, indicating their direct influence on brain damage, as assessed in patients experiencing spontaneous subarachnoid hemorrhage at 24 h, 72 h, and one week following the hemorrhagic event." (PMID 40649119, 2025). "GFAP levels and S100B levels (but not NSE levels) after subarachnoid hemorrhage correlated with the clinical condition and the degree of hemorrhage of patients on admission." (PMID 26714784, 2015).
ZIKV infection (14 papers, 2017 to 2026). "Astrocytes in our model also exhibited susceptibility to ZIKV infection, consistent with previous reports, and showed marked GFAP overexpression together with pronounced morphological alterations." (PMID 41296740, 2025). "Although GFAP has several phosphorylation sites, very little is known about their modification following Zika virus infection, and will be studied in the future." (PMID 29022904, 2017). "Among those 2% of ZIKV-infected cells, nearly 90% were GFAP+ astrocytes, which were 8 times more abundant than Tuj1+ neurons, suggesting astrocytes were more permissive to ZIKV infection than neurons, and could serve as a potential ZIKV reservoir." (PMID 33657175, 2021). "However, after ZIKV infection, the amount of Tuj1+ cells reduced to 10%, while GFAP+ cells increased to 66%, indicating that ZIKV promoted astrocytic differentiation but limited neuronal production in neural stem cells." (PMID 33657175, 2021). "To assess their changes in the retina after ZIKV infection, we stained retinal flatmounts or sections with antibody against-GFAP, a marker for astrocytes and gliosis, or antibody against-glutamine synthetase (GS), which is expressed in Müller cells and their processes." (PMID 34034828, 2021). "GFAP and vimentin increase found in infected astrocytes suggest that ZIKV infection could be actively inducing a reactive state." (PMID 31988337, 2020). "It is noted that cultured astrocytes have lower levels of GFAP expression than in vivo, and all cultures showed expression of several genes relating to astrocyte development, which we feel supports the use of this model to explore signaling patterns following ZIKV infection." (PMID 33405202, 2021). "Since GFAP is also a marker of astrocytes that participate in the neural immune response, this increase in GFAP-positive cells may result from an enhanced immune response to ZIKV infection." (PMID 29476066, 2018). "We also observed increased immunoreactivity for the astrocyte marker GFAP in hippocampi but not cerebral cortices of P30 offspring exposed to maternal ZIKV infection, while staining for the myeloid cell marker IBA1 was unchanged in either brain region." (PMID 41525323, 2026). "Sections from naïve (not shown) and IgR pups demonstrated base-line levels of GFAP and Iba1 labeling in the absence of ZIKV infection." (PMID 35379362, 2022). "When looking into the rate of ZIKV infection, only around 1% cells were infected at the end of differentiation (Day 16), and the majority of ZIKV+ cells were GFAP+ astrocytes with very few Tuj1+ neurons, indicating differentiated astrocytes may be a potential ZIKV reservoir." (PMID 33657175, 2021). "Infrared and immunofluorescent imaging was used to assess the effect of ZIKV on neuroinflammation by detecting the expression of Iba1 and GFAP in brain sections from 10 of the mice that succumbed to ZIKV infection (brains from four of the mice were not analyzed due to artifactual damage)." (PMID 28068342, 2017). "In our studies with ZIKV infections, the presence of MAP-2 (neuronal marker) and absence of GFAP (astrocyte glial marker) clearly indicated the complete neuronal differentiation of progenitor cells to cortical neurons in our studies with ZIKV infections." (PMID 30866785, 2019).
encephalomyelitis (13 papers, 2019 to 2025). Inflammation of the brain and the spinal cord. "It has been reported that the development of EBV encephalomyelitis can be associated with autoimmune reactions, such as GFAP astrocytic disease." (PMID 36482607, 2022). "In a rodent model of acute monophasic GFAP encephalomyelitis, brain inflammation starts two days after T cell transfer and reaches a peak at day five to seven, after which the animals fully recover." (PMID 38310187, 2024). "Anti-GFAP encephalomyelitis is characterized by T2/FLAIR hyperintensities in the semi-oval center white matter, accompanied by radial perivascular contrast enhancement." (PMID 38473365, 2024). "This article reports a relatively rare case of a patient with EBV encephalomyelitis complicated with GFAP-IgG antibody positive." (PMID 36482607, 2022). "Recently, antibodies against the alpha isoform of the glial-fibrillary-acidic-protein (GFAPα) were identified in a small series of patients with encephalomyelitis." (PMID 34635185, 2021). "Discovered in 2016, anti-GFAP encephalomyelitis is an astrocytopathy that may result in an acute meningoencephalomyelitis." (PMID 38473365, 2024). "It was also reported that a rare case of EBV encephalomyelitis with negative GFAP‐IgG at onset turned positive GFAP‐IgG after 15 days." (PMID 37458208, 2023).
hippocampal atrophy (13 papers, 2022 to 2026). "GFAP also showed significant correlations with frontotemporal–parietal cortical atrophy, which aligns with the previous study in which GFAP levels were negatively associated with hippocampal atrophy and lower cortical thickness in temporal and parietal regions in the AD continuum." (PMID 41287525, 2025). "In addition, they found an association between serum GFAP and hippocampal atrophy." (PMID 38489178, 2024). "Consistent with previous findings, we found a strong age effect in astrocyte activity measured by plasma GFAP, axonal degeneration measured by plasma NfL, and hippocampal atrophy." (PMID 39080744, 2024). "The aim of this study is to investigate whether astrocyte activation is correlated with hippocampal atrophy, and to assess the potential of glial fibrillary acidic protein (GFAP) as a biomarker for diagnosing MCI among community-dwelling older individuals." (PMID 39534430, 2024). "Interestingly, individuals with a five‐fold higher concentration of GFAP at baseline displayed accelerated hippocampal atrophy and decreases in cortical thickness over the up to 16‐year follow‐up period, suggesting that elevations in GFAP may predict future risk of neurodegeneration." (PMID 36056631, 2022).
intracranial hemorrhage (13 papers, 2013 to 2025). Bleeding within the SKULL, including hemorrhages in the brain and the three membranes of MENINGES. "Increased GFAP plasma concentrations in patients with acute coma identify intracranial hemorrhage with high diagnostic accuracy." (PMID 38581002, 2024). "The aim of this study was to test the diagnostic value of a GFAP point-of-care device to rapidly differentiate intracranial hemorrhage from other causes of acute coma in the prehospital phase." (PMID 38581002, 2024). "GFAP values above 1000 pg/mL were associated with intracranial hemorrhage or another primary cerebral cause of coma in all cases, allowing reliable biomarker-based triage of patients with low error rate." (PMID 38581002, 2024). "Our study demonstrated that prehospital plasma GFAP measurements on a point-of-care platform identify intracranial hemorrhage as the underlying cause of acute coma with high diagnostic accuracy." (PMID 38581002, 2024). "This increases the diagnostic accuracy of GFAP for this indication (i.e. increasing the sensitivity for detecting intracranial hemorrhage)." (PMID 38581002, 2024). "Our study confirmed that any type of intracranial hemorrhage causes significant GFAP release." (PMID 38581002, 2024). "The aim of this prospective study was to test whether prehospital GFAP measurements on a point-of-care device have the potential to rapidly differentiate intracranial hemorrhage from other causes of acute coma." (PMID 38581002, 2024). "Another recent-published study with 142 large vascular occlusive stroke patients confirmed a significant correlation between serum GFAP levels and symptomatic intracranial hemorrhage after endovascular treatment." (PMID 40421099, 2025). "Recently, glial fibrillary acidic protein (GFAP) has been identified as a biomarker of intracranial hemorrhage." (PMID 38581002, 2024). "GFAP plasma concentrations were strongly elevated in patients with intracranial hemorrhage (n = 51) compared to all other coma etiologies (3352 pg/mL [IQR 613–10001] vs. 43 pg/mL [IQR 29–91.25], p < 0.001)." (PMID 38581002, 2024). "The high PPV in patients with increased GFAP values opens the door to an earlier treatment of patients with severe intracranial hemorrhage." (PMID 38581002, 2024). "Specificity of 89.2%, positive predictive value of 88.9%, and negative predictive value of 100%, demonstrating that serum GFAP has promising diagnostic value for detecting intracranial hemorrhage in patients with acute stroke." (PMID 40649119, 2025). "A GFAP test prior to any prehospital anticoagulation administration could help to minimize fatal consequences resulting from undiagnosed intracranial hemorrhage." (PMID 38581002, 2024). "In addition to ICH, our data demonstrated that all intracranial hemorrhage cases, including both extra-axial and parenchymal hemorrhage, have significantly elevated GFAP levels." (PMID 24260364, 2013). "In contrast, the combined measurement of GFAP and UCH-L1 is suited for detecting acute injury and the presence of intracranial hemorrhage within the first several hours post-trauma." (PMID 41586414, 2025). "Median plasma GFAP was 3352 pg/mL (IQR 613–10,001) in patients with intracranial hemorrhage as defined above, and 43 pg/mL (IQR 29–91.25) in patients with other etiologies (p < 0.001)." (PMID 38581002, 2024). "Three patients were found to have intracranial hemorrhages on SWI, all of whom had very high GFAP levels." (PMID 24260364, 2013).
intracranial hemorrhage (continued). "A recent study demonstrated that glial fibrillary acidic protein and ubiquitin c-terminal hydrolase L1 can be used in combination to safely both rule in and rule out intracranial hemorrhage and to some extent predict the need for neurological intervention." (PMID 31089789, 2021).
optic neuritis (13 papers, 2011 to 2025). Optic neuritis is inflammation of the optic nerve, the nerve that carries the visual signal from the eye to the brain.The conditionmay cause sudden, reduced vision in the affected eye(s). "Glial fibrillary acidic protein (GFAP) antibody-associated disorder is another important differential diagnosis, as it can present with diverse neurological symptoms, including optic neuritis and optic disc edema." (PMID 40137464, 2025). "GFAP antibodies have also been associated with another, rarer phenotype: bilateral optic neuritis with severe visual impairment and a limited response to acute-phase treatment including high doses of intravenous steroids and plasma exchange." (PMID 37958968, 2023). "This study aimed to observe the clinical characteristic and MRI changes of GFAP-Ab-positive optic neuritis (ON)." (PMID 37101204, 2023). "In the current study, we report the frequency of GFAP-Ab-positive in patients with optic neuritis (ON) and defined the clinical and MRI changes of GFAP-Ab-positive ON." (PMID 37101204, 2023). "The aim of this study was to ascertain the extent to which serum GFAP levels can distinguish between an episode of optic neuritis (ON) related to NMO spectrum disease and ON from other causes." (PMID 21876753, 2011). "The serum GFAP level was measured after variable time intervals (until 210 days) following the acute optic neuritis episode onset." (PMID 21876753, 2011). "GFAP was detectable in the serum of all but three patients (two patients with MS-related ON and one with recurrent optic neuritis)." (PMID 21876753, 2011). "Serum GFAP levels need to be measured in patients presenting with acute isolated ON for the first time, with no known medical history, in order to accurately determine the role of GFAP in the diagnosis of optic neuritis." (PMID 21876753, 2011). "The fact that GFAP-IκBα-dn were significantly protected from RGC death compared to WT mice is a further demonstration that toxic pathways activated in astrocytes are the initial determinant in the cascade of events leading, ultimately, to permanent loss of visual function in optic neuritis." (PMID 22963651, 2012). "Glial pathology in NMO related optic neuritis is reflected in elevated serum GFAP levels independently of whether or not there is extra-optic nerve disease." (PMID 21876753, 2011). "This study has shown that Glial pathology in NMO related optic neuritis is reflected in elevated serum GFAP levels independently of whether or not there is extra-optic nerve disease." (PMID 21876753, 2011).
Seizure (13 papers, 2014 to 2025). A seizure is an intermittent abnormality of nervous system physiology characterized by a transient occurrence of signs and/or symptoms due to abnormal excessive or synchronous neuronal activity in the brain. "Seizure duration was found to be positively correlated with GFAP levels, and levels measured in patients with SE were significantly higher compared to those achieved in patients without SE." (PMID 37569895, 2023). "In human subjects diagnosed with epileptic seizures, serum GFAP level is significantly increased compared to healthy controls." (PMID 36362260, 2022). "Since the infantile form of AxD is frequently characterized by the occurrence of epileptic seizures, ideally, it should be advisable that compounds able to suppress or modulate GFAP expression may also have antiepileptic activity." (PMID 34950024, 2021). "Seizures are seen in most infantile or type I AxD patients, and kindling has been shown in rat models to transiently increase the expression of GFAP even in the contralateral hippocampus." (PMID 26478912, 2015). "We posit that electroencephalography and imaging are helpful for patients with early acute epileptic seizures or isolated epileptic seizures without any cause and recommend that GFAP antibody testing be carried out as soon as possible to determine the diagnosis." (PMID 40538658, 2025). "To determine whether tissue injury or macrophage-related inflammation is associated with the GCD phenotypes, we examined the hippocampal expression of injury markers GFAP and CD163 in 6 seizure patients and 10 controls." (PMID 32317027, 2020).